CD300LF (CD300 molecule like family member f)
Description:
Acts as an inhibitory receptor for myeloid cells and mast cells. Positively regulates the phagocytosis of apoptotic cells (efferocytosis) via phosphatidylserine (PS) recognition; recognizes and binds PS as a ligand which is expressed on the surface of apoptotic cells. Plays an important role in the maintenance of immune homeostasis, by promoting macrophage-mediated efferocytosis and by inhibiting dendritic cell-mediated efferocytosis (By similarity). Negatively regulates Fc epsilon receptor-dependent mast cell activation and allergic responses via binding to ceramide and sphingomyelin which act as ligands. May act as a coreceptor for interleukin 4 (IL-4). Associates with and regulates IL-4 receptor alpha-mediated responses by augmenting IL-4- and IL-13-induced signaling (By similarity). Negatively regulates the Toll-like receptor (TLR) signaling mediated by MYD88 and TRIF through activation of PTPN6/SHP-1 and PTPN11/SHP-2. Inhibits osteoclast formation. Induces macrophage cell death upon engagement (By similarity).
Synonyms: CLM-1; IREM-1; IgSF13; CD300f; CLM1; IREM1; NKIR; LMIR3
Tractability: Antibody: UniProt places it where antibodies can reach, with high confidence; its Gene Ontology location is reachable by antibodies, with high confidence; UniProt predicts a signal peptide or a membrane-spanning region. PROTAC: its protein half-life has been measured.
Gene: Protein-coding gene on chromosome 17 (74,694,308 to 74,712,981, reverse strand). Ensembl gene ENSG00000186074.
Subcellular location: Cell membrane
Pathways (Reactome):
Immune System: Immunoregulatory interactions between a Lymphoid and a non-Lymphoid cell
Gene Ontology:
Molecular function: ceramide binding; identical protein binding; protein binding; interleukin-4 receptor binding; phosphatidylserine binding; transmembrane signaling receptor activity
Biological process: negative regulation of mast cell activation; negative regulation of MyD88-dependent toll-like receptor signaling pathway; TRIF-dependent toll-like receptor signaling pathway; immune response-activating signaling pathway; interleukin-13-mediated signaling pathway; negative regulation of apoptotic cell clearance; positive regulation of apoptotic cell clearance; positive regulation of interleukin-4-mediated signaling pathway
Cellular component: plasma membrane
Genetic constraint (gnomAD): Loss-of-function variants: 27 observed, 33.65 expected, observed/expected ratio (o/e) 0.8, 90% interval 0.59 to 1.11. The upper end of that interval is the gene's LOEUF score, 1.11, which puts it in group 4 of 6, group 1 being the genes least tolerant of losing a copy. Missense variants: 342 observed, 368.63 expected, observed/expected ratio (o/e) 0.93, 90% interval 0.85 to 1.01. Synonymous variants: 136 observed, 149.82 expected, observed/expected ratio (o/e) 0.91, 90% interval 0.79 to 1.05.
Homologues: Orthologues: chimpanzee CD300LF (97% identical), macaque CD300LF (86% identical), dog CD300LF (61% identical), rabbit CD300LF (58% identical), guinea pig CD300LF (56% identical), mouse Cd300lf (54% identical), rat Cd300lf (52% identical), mouse Cd300ld (28% identical), rat Cd300le (27% identical), mouse Cd300ld2 (27% identical), mouse Cd300ld3 (27% identical), mouse Cd300ld4 (27% identical), and 3 more. Paralogues in human: CD300LD (34% identical), CD300LB (33% identical), CD300A (27% identical), CD300C (21% identical), CD300E (21% identical), CD300H (20% identical), PIGR (19% identical), CD300LG (18% identical), FCMR (17% identical), FCAMR (17% identical), TREML1 (17% identical), TREM2 (15% identical), and 1 more.
Diseases named in the same sentence as CD300LF in open-access papers:
CD300LF is named in the same sentence as 65 diseases in open-access papers, as found by Europe PMC text mining. Sharing a sentence is not in itself a finding about the gene and the disease. The quoted sentences say what the papers report.
injury (2 papers, 2023 to 2024). Damage inflicted on the body as the direct or indirect result of an external force, with or without disruption of structural continuity. "In summary, our findings highlight CD300LF as a critical molecular regulator modulating the adverse actions of microglia following acute brain injury and propose a novel therapeutic approach to enhance outcomes for patients with TBI." (PMID 38965803, 2024).
viral infection (2 papers, 2020 to 2024). "We demonstrated that CD300lf is essential for detectable viral infection at multiple time points with diverse MNoV strains as measured by plaque assay, qPCR, and serologic response." (PMID 32251490, 2020). "We also identify CD300lf-independent viral infection in the setting of extra-intestinal challenge in immunodeficient mice, suggesting a potential role for CD300ld or other receptors in this non-physiological infection route." (PMID 32251490, 2020). "Although the replication speed of the reporter viruses seemed to be slower than the WT virus, these mutations did not change their MNV properties: they used CD300lf as a receptor and MNV antisera inhibited reporter virus infection." (PMID 38226813, 2024).
acute liver failure (1 paper, 2024). Rapid deterioration of liver function causing encephalopathy and coagulopathy. "Consistently, in a mouse model of acute liver failure, CD300LF-mRNA-macrophages facilitated organ recovery from acetaminophen-induced hepatotoxicity." (PMID 39229455, 2024).
celiac disease (1 paper, 2020). An autoimmune genetic disorder with an unknown pattern of inheritance that primarily affects the digestive tract. "Ten of these cDC2 high-confidence Runx3 targets were common to those in RM and human homologs of four, CD300LF, IFIH1, IRF4 and SLC22A5 (mouse Slc22a21) harbored SNPs associated with IBD, CD, UC and/or celiac disease." (PMID 32453801, 2020). "Of note, the human homologs of four of the CD11b+ DC Runx3 targets, CD300LF, IFIH1, IRF4 and SLC22A5 (mouse Slc22a21) harbored SNPs associated with IBD, CD, UC and/or celiac disease and the two former genes are common Runx3 targets in RM and CD11b+ DC." (PMID 32453801, 2020).
epilepsy (1 paper, 2021). A brain disorder characterized by episodes of abnormally increased neuronal discharge resulting in transient episodes of sensory or motor neurological dysfunction, or psychic dysfunction. "The second novel miR-324-5p target identified in this study, Cd300lf, has no direct link to epilepsy in the literature." (PMID 34001919, 2021).
infection (28 papers, 2014 to 2025). The state of being infected such as from the introduction of a foreign agent such as serum, vaccine, antigenic substance or organism. "In mice, TCs express high levels of murine norovirus receptors, CD300lf, enabling infection, while also serving as viral reservoirs causing chronic infections and viral shedding for weeks following the acute phase of infection." (PMID 35237268, 2022). "Therefore, substantive discussion on the natural variation of CD300LF, including its potential causes and consequences, would require a robust understanding of its function outside the context of infection." (PMID 32581099, 2020). "Given the distinct target cell types, tissue tropism, and pathogenesis between MNoV strains, we next tested whether Cd300lf-/-Stat1-/- mice were susceptible to MNoVCR6 infection." (PMID 32251490, 2020). "We mined a previous genome-wide CRISPR activation screen identifying anti-norovirus restriction factors for MNVCW3 and MNVCR6 infection of HeLa-CD300lf-expressing cells." (PMID 41251344, 2025). "Ectopic expression of the mouse CD300lf protein, the entry receptor for MNV, renders HEK293T cells susceptible to infection with the virus." (PMID 38393950, 2024). "Second, we used real-time quantitative reverse transcription-PCR (qRT-PCR) to measure the expression levels of several candidate RIDD genes, including Bloc1s1, Cd300lf, Diras2, and Txnip during infection." (PMID 35587649, 2022). "While the mechanism and impact of this conformational change are not yet clear for HuNoV, for murine norovirus such a conformational change contributes to increased accessibility to its cellular receptor CD300lf and enhancement of infection efficiency." (PMID 34262046, 2021). "Cd300lf+/- mice had a significantly higher anti-MNoV IgG and IgM response consistent with resistance of Cd300lf-/- mice to MNoVCW3 infection." (PMID 32251490, 2020). "BV2 and BJAB cells were chosen for this assay, as they produced the highest viral titer in infection experiments yet showed varied ability to support replication when expressing IL/CD300LF." (PMID 32581099, 2020). "While C57BL/6J CD300LF (B6/CD300LF) expression confers MNV infection capacity to BV2-KO cells, expression of I/LnJ CD300LF (IL/CD300LF) is insufficient to permit infection of BV-2KO cells, similar to the results obtained using BMDMs." (PMID 32581099, 2020). "We report that both CD300ld and CD300lf are sufficient for infection by diverse MNoV strains in vitro." (PMID 32251490, 2020). "A 1:10 dilution of sera from Cd300lf+/- mice that cleared MNoVCW3 infection neutralized MNoVCW3in vitro as measured by BV2 cell viability." (PMID 32251490, 2020). "CD300lf is necessary for infection of MNoV-susceptible RAW 264.7 and BV2 cell lines while both CD300ld and CD300lf are sufficient to confer susceptibility to cell lines from different species when ectopically expressed." (PMID 32251490, 2020). "At 24 hours post-infection (hpi), infectious virions were undetectable in Cd300lf-/- mice in the mesenteric lymph node (MLN), ileum, and colon, in contrast to Cd300lf+/- littermates." (PMID 32251490, 2020). "All Cd300lf+/+Stat1-/- and Cd300lf+/-Stat1-/- mice challenged with 106 PFU PO MNoVCR6 survived the seven-day infection." (PMID 32251490, 2020). "As a control, we first tested whether MNV infection of CD300lf-expressing Huh-7 cells would be sensitive to glutaminolysis inhibition." (PMID 38187600, 2023). "The capacity of a given MNV strain to undergo this contraction positively correlates with infection of cells expressing low abundance of the virus receptor CD300lf, supporting a model whereby virion contraction triggers infection of CD300lflo cell types that are responsible for diarrhea induction." (PMID 36389732, 2022). "Furthermore, in the resting conformation, the cellular receptor CD300lf is readily accessible, and thus infection efficiency is significantly enhanced." (PMID 32614892, 2020).
infection (continued). "Whether CD300lf is essential for genetically diverse MNoV strains, parenteral infection routes, or in the setting of immunodeficiency is unclear." (PMID 32251490, 2020). "To test whether CD300lf was essential for MNoVCW3 infection ex vivo, we challenged bone marrow-derived macrophages (BMDMs) from Cd300lf+/- or Cd300lf-/- mice with MNoVCW3." (PMID 32251490, 2020). "All Cd300lf+/+Stat1-/- succumbed to lethal infection by five dpi." (PMID 32251490, 2020). "CD300lf is thus essential for MNoVCW3 infection of murine BMDMs." (PMID 32251490, 2020). "Similarly, both CD300ld and CD300lf are sufficient for MNoVWU23, MNoVCR3, MNoVCR7, MNoVMNV3, and MNoVS99 infection." (PMID 32251490, 2020). "Here we determined that CD300lf is essential for infection of diverse murine norovirus strains in cell lines and in mice with normal immune systems demonstrating it’s the primary physiologic receptor for diverse murine norovirus strains independent of infection route." (PMID 32251490, 2020). "To determine whether CD300lf was essential for infection in vivo, we challenged Cd300lf+/- and Cd300lf-/- littermates with 106 PFU PO of either MNoVCW3, MNoVCR6, MNoVWU23, MNoVCR3, or MNoVCR7 and measured viral genomes seven days post-infection (dpi)." (PMID 32251490, 2020). "Taking the results together, while C57BL/6J CD300LF expression is necessary and sufficient for MNV infection in all contexts tested, the cell type-dependent functionality of I/LnJ CD300LF suggests the necessity of additional cell type-specific modifiers mediating MNV entry." (PMID 32581099, 2020). "To test the hypothesis that diverse MNoV strains differentially utilize CD300lf, we first tested whether CD300lf was necessary and sufficient for infection by these strains in vitro." (PMID 32251490, 2020). "Injection of zebrafish larvae with MNV (genogroup V) yielded no productive infection, most likely due to the fact that the receptors CD300lf and CD300ld are not encoded by zebrafish." (PMID 31536612, 2019). "Next, we asked whether CD300lf was required for infection by genetically diverse MNoV strains." (PMID 32251490, 2020). "CR6 infected CD300lf-overexpressing M12 cells as efficiently as MNV1 and WU23, confirming that the block to CR6 infection of M12 cells is due to its inability to use low levels of the host receptor." (PMID 36389732, 2022). "An epithelial cell line engineered to express the MNV receptor, CD300lf, has significant induction of IFN-λ upon MNV infection after priming with DCA compared to unprimed infection." (PMID 34071855, 2021). "It was confirmed that this was the receptor from studies showing that knocking out Cd300lf in BV2 cells blocked infection by MNV and treating the cells with antibodies to CD300lf blocked MNV attachment." (PMID 32516952, 2020). "To directly test the role of CR6 NS1/2 cleavage on initial infection of IECs, we used a previously characterized CD300lf-transduced IEC cell line (M2C-CD300lf, hereafter M2C), which can be infected by CW3 and CR6." (PMID 31329638, 2019). "In contrast to the strain-dependent infection of IECs in vivo, CW3 and CR6 can replicate to similar titer in a cultured IEC cell line (M2C) that ectopically expresses CD300lf." (PMID 31329638, 2019). "As CD300lf is a universal MNV receptor required for both in vitro and in vivo infection, we hypothesized that unknown MNV restriction factors contribute to MNV strain-specific differences." (PMID 41251344, 2025). "To confirm that barcode sequences recovered from mice were from replicating virus and not the administered inoculum, we inoculated mice lacking the MNoV receptor CD300LF which are resistant to infection." (PMID 38701091, 2024). "Though the role of BA was not evaluated in a separate receptor study, CD300lf is required for infection of tuft cells by the persistent strain CR6." (PMID 34071855, 2021).
infection (continued). "For the nonpersistent CW3 strain, infection of myelomonocytic cells is reduced by CD300lf disruption and viral levels detected during infection of other cell types (e.g., B cells) is unaffected." (PMID 34071855, 2021). "To test whether CD300lf was essential for parenteral infection routes, we bypassed the gastrointestinal tract by administering 107 PFU MNoVCW3 intraperitoneally (IP) to Cd300lf-/-Stat1-/- mice." (PMID 32251490, 2020). "Expression of C57BL/6J CD300LF in cells noninfectible by MNV makes the cells permissive to MNV infection, demonstrating the entry step as a major barrier for MNV infection." (PMID 32581099, 2020). "Consistent with our prior findings, both CD300ld and CD300lf are sufficient for infection by MNoVCW3 as measured by expression of the MNoV non-structural protein NS6/7 by flow cytometry." (PMID 32251490, 2020). "Our in vitro studies of infection in IEC monolayers support this hypothesis, and the dispersed nature of CD300lf-expressing tuft cells poses a strong selective pressure for efficient spread across receptor-negative stretches of the intestinal epithelium." (PMID 31329638, 2019). "Thus, we stably expressed C57BL/6J or I/LnJ CD300LF via lentiviral transduction in a variety of cell types that do not express murine CD300LF and thus are not susceptible to MNV infection, including mouse embryonic fibroblasts (MEFs) and human cell lines 293T, HeLa, BJAB, and Jurkat." (PMID 32581099, 2020). "Compared to lethal infection of Cd300lf+/-Stat1-/- littermates, intraperitoneal CR6 infection of mice lacking MNoV receptor CD300LF is significantly abrogated and is non-lethal." (PMID 33705489, 2021).
tumor (4 papers, 2015 to 2025). "From these six genes two were higher expressed in GAMs derived from the RCAS model (CD300lf and Cd200r4), two genes were expressed at similar levels in GAMs in both tumor models (Trem1 and Sh2d1b1), and two genes were higher expressed in GAMs derived from the GL261 model (Uck2 and Creb5)." (PMID 25658639, 2015). "CD8A, DOK2, CX3CR1, TYROBP, CXCL9, CD300LF, and IFNG were identified as significant DEGs between tumor samples with high and low CD200R1 expression." (PMID 32635224, 2020).
cancer (2 papers, 2023 to 2025). A tumor composed of atypical neoplastic, often pleomorphic cells that invade other tissues. "We found that CD300LB, CD300C, and CD300LF were significantly hypomethylated in almost all cancer types as compared to normal samples." (PMID 35642341, 2023).
CD300LF also shares sentences with these, for which no sentence is quoted: acute myeloid leukemia (3 papers); allergic disease (3); autoimmune disease (3); colitis (3); Crohn disease (3); multiple sclerosis (3); systemic lupus erythematosus (3); Allergy (2); Autoimmunity (2); cerebral malaria (2); experimental autoimmune encephalomyelitis (2); gastric cancer (2); Sepsis (2); allergic rhinitis (1); Alzheimer disease (1); bacterial infections (1); bacterial sepsis (1); breast carcinoma (1); demyelination (1); Depression (1); disseminated candidiasis (1); eosinophilia (1); Erythema (1); fungal infection (1); glioblastoma (1); Glucose intolerance (1); helminth infection (1); hematological malignancies (1); histiocytic lymphoma (1); infectious disease (1).
A further 27 diseases each share a sentence with CD300LF in 1 paper.